PKD1 (polycystin 1, transient receptor potential channel interacting)
Diseases named in the same sentence as PKD1 in open-access papers (continued):
Sharing a sentence is not in itself a finding about the gene and the disease.
breast tumor (8 papers, 2009 to 2020). "Consistent with these in vitro data, our in vivo analysis of PKD1 expression in 152 ERα-positive breast tumours from tamoxifen-treated patients showed that high PKD1 expression is associated with less tamoxifen responsiveness." (PMID 25287328, 2014). "In primary breast tumors, PKD1 protein expression was detected both in tumor cells and in cells from the tumor microenvironment, including fibroblasts, mononuclear immune cells and endocytes." (PMID 29796183, 2018). "Specifically, it has been shown that PKD1 is downregulated in invasive human breast tumors as compared to normal breast tissues." (PMID 30419840, 2018). "Together, these data indicate that PKD1 is likely to play a specific role in estrogen-independent breast tumors." (PMID 29796183, 2018). "Most interestingly, high PRKD1 expression is a poor prognostic factor in ER+ tamoxifen-treated breast tumors, suggesting that PKD1 participates to endocrine therapy resistance in the clinics." (PMID 29796183, 2018). "PKD1 has been previously shown to be a prognostic factor in ERα+ tamoxifen-resistant breast tumors and PKD1 overexpression confers estrogen independence to ERα+ MCF7 cells." (PMID 29796183, 2018). "This suggests that decitabine-mediated inhibition of breast tumor cell metastasis is dependent on reexpression of PKD1." (PMID 23971832, 2013). "Overexpression of PKD1 increase the growth of BPA-exposed breast tumor xenografts in vivo." (PMID 33330580, 2020). "We explored how PKD1 may sensitize cancer cells to BPA by testing whether BPA can increase breast tumor growth by regulating cell survival and/or cell proliferation, in which PKD1 plays a crucial role." (PMID 32082170, 2019). "Moreover, PKD1 overexpression increased the growth of BPA-exposed breast tumor xenografts in vivo in athymic female Swiss nude (Foxn1nu/nu) mice." (PMID 32082170, 2019). "The poorer prognosis of TNBC expressing high PRKD1 levels suggests that PKD1 plays a role in the biology of TN breast tumors and could represent a therapeutic target for their treatment." (PMID 29796183, 2018). "Therefore, PKD1 mRNA levels were quantified by qRT-PCR in 152 primary ERα-positive breast tumours from patients treated with primary surgery followed by adjuvant tamoxifen alone." (PMID 25287328, 2014). "This suggests that both PKD1 expression and methylation of its promoter could serve to determine the invasive potential of breast tumors." (PMID 23971832, 2013). "Therefore, to assess the specific effects of decitabine-induced PKD1 reexpression on an invasive phenotype of breast tumor cells, we used our lentiviral system comprising a scr-shRNA and two different PKD1-specific shRNA sequences to prevent PKD1 reexpression." (PMID 23971832, 2013). "We next analysed if the decreased expression of PKD1 is one of the means by which breast tumour cells may increase their invasive potential." (PMID 19243594, 2009). "Our data showing reduced PKD1 protein expression in invasive breast cancer is also in consensus with published transcriptional microarray data profiling over 350 surgically excised, advanced breast tumour tissues." (PMID 19243594, 2009). "Therefore, due to its crucial role in breast tumor growth and development, we asked in this study whether PKD1 may be a molecular target of BPA." (PMID 32082170, 2019). "Therefore, we next examined whether PKD1 reexpression induced by decitabine was able to inhibit breast tumor cell infiltration of the lungs." (PMID 23971832, 2013). "PKD1 specifically mediates BPA-induced cell proliferation, clonogenicity, and anchorage-independent growth of breast tumor cells." (PMID 32082170, 2019). "Therefore, the relationship between PKD1 and ERα in the context of cell response to BPA needs to be further considered, not only in breast tumors, but also in all ERα- and PKD1-expressing tissues, regardless of cell phenotype, tumorigenic or not." (PMID 32082170, 2019).
breast tumor (continued). "In our cohort, we did observe that PKD1 is down-regulated in primary breast tumors as compared to normal breast tissue (data not shown) and we also showed that high PRKD1 mRNA levels are predictive of a poorer prognosis in both the entire cohort and the TNBC subgroup." (PMID 29796183, 2018). "Thus, we first analyzed PKD1, PKD2 and PKD3 expressions in a large series of primary breast tumors." (PMID 29796183, 2018). "However, no data are available on how PKD1 expression is negatively regulated during breast tumor progression." (PMID 23971832, 2013). "We found that PKD1 is highly expressed in epithelial ductal tissue of human normal breast samples, but is reduced in its expression in more than 95% of invasive human breast tumour samples (representative pictures of normal and tumour tissue are in Figures 1a1 to 1a4)." (PMID 19243594, 2009).
diabetes (8 papers, 2019 to 2025). "Based on a genome-wide association study, PKD1 has been proposed as a novel gene for the prediction of coronary artery disease in patients with type 1 diabetes mellitus." (PMID 31757932, 2019). "The shorter duration of diabetes and earlier renal dysfunction in proband B may be partly attributed to the PKD1 mutations in her mother, who also had diabetic nephropathy." (PMID 39556225, 2024). "It was shown that PKD1 plays an important role in the regulation of insulin secretion and the survival of β-cells in the pathogenesis of diabetes mellitus." (PMID 32466765, 2020).
colorectal cancer (7 papers, 2014 to 2025). A primary or metastatic malignant neoplasm that affects the colon or rectum. "In colorectal cancer, high PKD1 and PKD2 expressions have been associated with reduced recurrence-free survival and overall survival of the patients." (PMID 40299470, 2025). "Moreover, in vitro data in colorectal cancer demonstrate that both PKD1 and PKD2 promote an epithelial–mesenchymal transition (EMT)." (PMID 40299470, 2025). "Although the remaining 7 genes (PKD1, FAM38A, WDR81, TMEM136, SLC36A1, SLC26A6, IGFLR1) are mutated in >10% of the colorectal cancer cell lines, literature searches did not reveal evidence of the functional role or therapeutic potential of these genes in colorectal cancer." (PMID 25193853, 2014). "p38 inhibited the PKD1 activation, a kinase that phosphorylates CREB at Ser133, there by promoting apoptosis in response to selenite in colorectal cancer cells." (PMID 40860181, 2025). "Fusobacterium nucleatum, a gram-negative anaerobic bacillus, is mainly associated with colorectal cancer patients positive for the CpG island methylator phenotype, although hypermethylation in genes such as MLH1, CDKN2A, MTSS1, RBM38, PKD1, PTPRT, and EYA4 has also been described." (PMID 37614819, 2023). "PKD1 expression was shown to be downregulated in higher-grade colon cancer compared with non-neoplastic samples, and overexpression of PKD1 in human SW480 colorectal cancer cells inhibited cell proliferation, clonogenicity, and delayed tumor growth in a xenograft mouse model." (PMID 33807058, 2021).
intracranial aneurysms (7 papers, 2014 to 2025). "Characteristics of the datasets used to test the association between intracranial aneurysms, and the genes PKD1 and SMAD2." (PMID 40172005, 2025). "PKD1 and PKD2 patients seem equally likely to develop intracranial aneurysms, while patients with specific mutations of PKD1 are more likely to have vascular complications." (PMID 39628750, 2024). "On the other hand, in both ADPKD and KS there is an elevated frequency of intracranial aneurysms and, in the case of associated variants in PKD1 protein and KS, it is expected to have at least additive intracranial aneurysms in disease presentation." (PMID 35327948, 2022). "Vascular abnormalities in ADPKD such as intracranial aneurysms are probably linked to mutations in PKD1 or PKD2, an integral membrane protein involved in cell-cell and cell-matrix interactions." (PMID 25763300, 2015). "Patients with PKD1 and PKD2 seem equally likely to develop intracranial aneurysms, while patients with mutations to the 5' half of PKD1 may more likely have vascular complications." (PMID 24571546, 2014). "In fact, our patient with an LP variant in PKD1, KS, and a compound heterozygous GS-associated variant showed a severe phenotype of ADPKD, characterized by the development of early CRF (at 27 years old) and rapid evolution to ESRD (at 40 years old), associated with an intracranial aneurysm." (PMID 35327948, 2022). "The genes responsible, PKD1 and PKD2, respectively, appear to have equivalent expression of intracranial aneurysms and play a direct pathogenetic role in aneurysm formation." (PMID 24571546, 2014).
brain aneurysm (6 papers, 2018 to 2023). A congenital or acquired aneurysm within the cranium. "The causative genes of brain aneurysm were three variants in PKD1, two variants in PKD2, and three variants in other genes." (PMID 36833371, 2023). "Cerebral aneurysms are more common in ADPKD patients with loss of function or missense mutations in the PC1-encoding PKD1 gene." (PMID 29472562, 2018). "Brain aneurysm was observed in eight patients (16%), and the causative genes were PKD1 (missense (n = 2), nonsense (n = 1)), PKD2 (missense (n = 1), splice-site (n = 1)), ZNF423 (missense), GLIS2 (missense) or PKHD1 (missense) or WDR19 (splice-site), and CEP164 (missense)." (PMID 36833371, 2023).
colon cancer (6 papers, 2014 to 2024). "This study aims to delineate a molecular association between PKD1 and β-catenin to develop an effective therapeutic strategy for colon cancer." (PMID 25149539, 2014). "PKD1 (Protein Kinase D1), a serine-threonine kinase, has been reported to modulate the β-catenin functions in colon cancer." (PMID 28054945, 2017). "The effect of PKD1 overexpression in attenuating β-catenin transcription activity was also detected in SW48 colon cancer cells." (PMID 25149539, 2014). "PKD1 overexpression inhibited the motility of colon cancer cells compared to control SW480-GFP cells." (PMID 25149539, 2014). "PKD1 overexpression (SW480-PKD1-GFP) significantly reduced the ability of colon cancer cells to form anchorage dependent colonies, compared to control cells." (PMID 25149539, 2014). "We examined the staining pattern of PKD1 expression in tissue of normal colon and colon cancer and demonstrated that PKD1 co-localized with β-catenin in normal colon tissues." (PMID 25149539, 2014). "The association between downregulation of PKD1 expression with the change in β-catenin localization in colon cancer seems to suggest a role for PKD1 in regulating β-catenin functions in colon cancer." (PMID 25149539, 2014). "Analysis of normal and colon cancer tissues reveals downregulation of PKD1 expression in advanced stages of colon cancer and its co-localization with β-catenin in the colon crypts." (PMID 25149539, 2014). "In-vitro investigation of the PKD1-β-catenin interaction in colon cancer cells reveal that PKD1 overexpression suppresses cell proliferation and clonogenic potential and enhances cell-cell aggregation." (PMID 25149539, 2014). "Herein, for the first time, we demonstrate that a serine-threonine kinase, Protein Kinase D1 (PKD1), modulates the functions of β-catenin to suppress colon cancer growth." (PMID 25149539, 2014). "For in-vitro analyses, we used SW480 and SW48 colon cancer cell lines to investigate and evaluate the effect of PKD1 overexpression on cellular characteristics." (PMID 25149539, 2014). "The in-vivo experiments suggests that PKD1 overexpression delayed tumor appearance and formed smaller tumors by modulating β-catenin functions in colon cancer." (PMID 25149539, 2014). "We have found a correlation of PKD1 downregulation with the aberrant expression and nuclear localization of β-catenin in human colon cancer tissues." (PMID 25149539, 2014). "Based on these results, we proposed that PKD1 functions as a tumor suppressor via modulating β-catenin signaling pathway and inhibiting nuclear β-catenin function to suppress colon cancer growth." (PMID 25149539, 2014). "Our results also revealed that PKD1 overexpression reduced the cellular motility of colon cancer cells by inhibiting the functions of the cofilin protein that are critical for the actin remodeling and cellular motility." (PMID 25149539, 2014). "The ability of PKD1 to inhibit motility of SW480 colon cancer cells was also confirmed using a wound-healing assay." (PMID 25149539, 2014). "In addition, PKD1 expression was downregulated in colon cancer tissues and this coincides with a corresponding change in the subcellular localization of β-catenin." (PMID 25149539, 2014). "Therefore, strategies for the up-regulation of PKD1 expression levels and/or activation in colon cancer cells are desired to modulate the nuclear β-catenin/Wnt signaling in colon cancer." (PMID 25149539, 2014). "Therefore, we evaluated the effect of PKD1 overexpression on motility of SW480 colon cancer cells using the agarose bead assay." (PMID 25149539, 2014). "In conclusion, our studies revealed a novel tumor suppressor function for PKD1 in colon cancer." (PMID 25149539, 2014). "Based on these results, we propose that PKD1 may act as a tumor suppressor in colon cancer by modulating the nuclear β-catenin/Wnt signaling." (PMID 25149539, 2014).
colon cancer (continued). "Additionally, the disruption of β-catenin/TCF complex formation was found on PKD1 expression that is important to regulate the proliferation and progression of colon cancer cells." (PMID 25149539, 2014). "Therefore, we screened a panel of five colon cancer cell lines for PKD1 expression using immunoblotting techniques." (PMID 25149539, 2014). "In order to investigate the expression profile of PKD1 in colon cancer tissues and quantitatively analyze changes in PKD1 or β-catenin expression, IHC analysis was performed on tissue microarray (TMA) slides containing normal (n=8) and colon cancer tissues (n=45) using chromogenic dyes." (PMID 25149539, 2014). "Thus, overexpression of PKD1 in colon cancer cells not only enhanced cell-cell interaction, but also inhibited cell motility." (PMID 25149539, 2014). "Moreover, functional assays including PKD1 overexpression in colon cancer cells inhibited cellular motility and enhanced cell-cell adhesion." (PMID 25149539, 2014). "Therefore, we used the SW480 colon cancer cells to stably overexpress PKD1 and analyze its role in the regulation of nuclear β-catenin activity and colon carcinogenesis." (PMID 25149539, 2014). "Herein, for the first time, we sought to investigate the role of PKD1 in colon cancer." (PMID 25149539, 2014). "Herein, we have investigated the role of PKD1 in colon cancer." (PMID 25149539, 2014). "A later study by the same group showed that overexpressing PKD1 in prostate, breast, and colon cancer cell lines led to accumulation of cells in G1 phase, which may be mediated through the direct phosphorylation of all three cell-division cycle 25 proteins (Cdc25s) (A, B, and C) by PKD." (PMID 33807058, 2021). "Thus, the identification of drug molecules that induce PKD1 overexpression/activation may be important for the development of novel therapeutic modalities to inhibit tumorigenesis and colon cancer progression." (PMID 25149539, 2014). "Thus an increase in PKD1 levels in colon cancer cells can inhibit the progression of colon cancer." (PMID 25149539, 2014). "After we confirmed that the designed peptides could be phosphorylated by active PKD1/PKCμ kinase, we treated HCT116 colon cancer cells and HepG2 liver cancer cells with those peptides." (PMID 32570757, 2020). "We also detected a trend in the progressive downregulation of PKD1 expression from non-neoplastic stage to Duke's stage B and Duke's stage C colon cancer." (PMID 25149539, 2014). "PKD1 overexpression also significantly decreased both anchorage dependent and anchorage independent clonogenic potential of SW48 cells indicating that the anti-carcinogenic functions of PKD1 in colon cancer were a cell line independent phenomenon." (PMID 25149539, 2014). "Our expression analysis revealed a conspicuous decrease in PKD1 levels in higher grade colon cancer samples compared to normal colon and early grade samples." (PMID 25149539, 2014). "In order to examine the molecular mechanisms regulating the cellular motility of the PKD1 overexpressing colon cancer cells, total protein lysates from SW480-PKD1-GFP or SW480-GFP cells were immunoblotted and examined for the expression of various motility related proteins." (PMID 25149539, 2014). "In order to investigate the functional role of PKD1 and the importance of PKD1-β-catenin interaction in colon cancer, we sought to overexpress PKD1 in a cell line that expresses low or no PKD1 and express high amounts of nuclear β-catenin, to mimic advanced stage colon cancer." (PMID 25149539, 2014). "However, the expression profile of PKD1 in colon cancer is not known." (PMID 25149539, 2014).
Hydrocephalus (6 papers, 2009 to 2024). Hydrocephalus is an active distension of the ventricular system of the brain resulting from inadequate passage of CSF from its point of production within the cerebral ventricles to its point of absorption into the systemic circulation. "They generated ubiquitous or brain-specific Pkd1 knockout mice, which encodes polycystin-1, and observed hydrocephalus at perinatal periods in both mouse lines." (PMID 25729351, 2015). "Mechanosensory proteins polycystic kidney disease 1 (Pkd1) and Pkd2 are expressed in primary cilia of RGCs, and their ablation leads to postnatal hydrocephalus and planar cell polarity defects in mouse ventricular epithelium." (PMID 27993979, 2017). "Our data strongly suggest that the hydrocephalus phenotype in Pkd1 mutant mice originates from the third ventricle, the first compartment to develop ciliated ependyma, and subsequently expands to the lateral ventricles." (PMID 19774080, 2009). "In fact, we have observed a mild hydrocephalus both in Pkd1 mutant embryos and in newborn conditional mice carrying a Nestin-Cre transgene." (PMID 19774080, 2009). "Consistent with this distribution, we observed hydrocephalus formation both in the ubiquitous knock-out embryos and in newborn mice with conditional inactivation of the Pkd1 gene in the brain." (PMID 19774080, 2009). "Consistent with this and the localization of PC-1 in brain tissue, we have found that inactivation of the Pkd1 gene using either a ubiquitous Cre or a Cre expressed in the central nervous system results in hydrocephalus, a relatively common condition in humans." (PMID 19774080, 2009). "Several mutations in Ccdc39, Celsr2, Celsr3, Cetn2, Dvls, FoxJ1, Hydin, Mdnah5, Pkd1, Tg737, Daple, Dnah14, Cfap43 and Cwh43 genes, which were related to the structure or function of motile cilia on ependymal cells, have been reported to develop hydrocephalus in animal models." (PMID 33874972, 2021). "The disruption of ependymal planar polarity and CSF circulation, as evidenced by the downregulated polycystin 1 (PKD1) and CELSR2, is also consistent with established hypotheses of hydrocephalus development." (PMID 39118132, 2024).
Bardet-Biedl syndrome (5 papers, 2019 to 2023). A ciliopathy with multisystem involvement. "The second approach focuses on Bardet-Biedl syndrome (BBS) proteins that bind to the polycystins and deliver Pkd1 to cilia." (PMID 35253003, 2022). "We developed a gene panel that includes 115 genes causing kidney disorders, including major genetic loci which account for ~ 85–90% of ADPKD and over 96% of Bardet-Biedl syndrome (BBS), namely PKD1-2 and BBS1-15, respectively." (PMID 33964006, 2021).